IRF7 (interferon regulatory factor 7)
Diseases named in the same sentence as IRF7 in open-access papers (continued):
Sharing a sentence is not in itself a finding about the gene and the disease.
infection (continued). "However, in HT-29 cells the levels of IRF7 decreased marginally at 36 hrs, but were shown unchanged at 24 hrs p.i., suggesting that TLR signaling may remain intact and be unaffected, and that TLR7/8 signaling may also function early and decrease only at the late stage of infection in HT-29 cells." (PMID 27007979, 2016). "Some of these molecules (IRF7, IRF9, STAT1, STAT2) are known ISGs and were upregulated in wild-type but not in IFNAR1−/−IL-28Rα−/− epithelia at 24 hours post infection." (PMID 24278020, 2013). "Despite the combined absence of IRF-3, IRF-5, and IRF-7, TKO mice still produced type I IFN after WNV infection, albeit at lower levels in the context of markedly enhanced infection." (PMID 23300459, 2013). "This suggests that macrophages can restrict WNV-NY infection through an alternative pathway that is independent of IRF-3, IRF-5, and IRF-7, possibly through IRF-1 and/or other transcription factors." (PMID 23300459, 2013). "In control DCs, IRF7 bound to both the Ifna4 and Ifnb genes after NDV infection, but not after mock infection." (PMID 19557165, 2009). "Mice that lack both IRF-3 and IRF-7 were highly vulnerable to lethal infection and cells lacking IRF-3 and IRF-7 had a markedly attenuated IFN-α response." (PMID 19798431, 2009). "IRF3 and IRF7 mRNA levels in HRV16 and HRV1B infection were not different from the mock." (PMID 34838080, 2021). "Irf-7−/− mice have a low spine density, which is not influenced by the LGTV infection." (PMID 32951602, 2020). "Likewise, absence of IRF7 slightly delays the IFN-I response in the CNS, thereby the onset of LCM following IC infection with LCMV-Arm." (PMID 30791575, 2019). "However, we did not detect increased expression or activation of IRF7 or IRF3, respectively, upon A/PR8 infection in wt or pkr−/− AM." (PMID 23468627, 2013). "IRF-7 was almost undetectable in RAW264.7 macrophages, with or without infection, but where low levels of IRF-7 could be seen in rare cells, an association with the L. donovani phagosome was not apparent." (PMID 20300600, 2010). "While knockdown of IRF3, IRF5, or IRF7 expression had no impact on the efficiency of infection establishment, we observed significant downregulation in IP-10 expression upon IRF5 or IRF3 knockdown and a trend toward significance upon knockdown of IRF7 expression in HIV-infected MDMs." (PMID 40493408, 2025). "The infection and proliferation of HCVbb in HuS-E/2 cells were enhanced by ectopic expression of a dominant-negative form of IRF-7, but not that of IRF-3, suggesting that IRF-7, rather than IRF-3, plays a primary role in regulation of HCV proliferation in these cells." (PMID 24587086, 2014). "IRF-7, together with IRF-3, is known to play a pivotal role in the induction of IFN-α and IFN-β genes through binding with PRDI in cells infected with virus, although it was suggested that IRF-7, rather than IRF-3, is important to suppress the infection and replication of HCV in the cells." (PMID 24587086, 2014). "Interestingly, whereas TLR4 inhibition (TAK-242, 10 μM) did not alter enhanced OAS1 and IRF7 expression in response to hypoxic priming and SARS-CoV-2 infection, it completely abolished the expression of chemokine ISGs CCL2 and CXCL10, despite the fact that the infection rate was not affected." (PMID 37377965, 2023).
tumor (142 papers, 2009 to 2026). "Activated CD8+ T cells, especially the resident memory effect T cells, predominate in IRF7-C435A mutated tumor, while CD8_Naive and CD4_Naive predominate in IRF7-WT tumors." (PMID 41535256, 2026). "We observed similar effects following co-injection of gRNAs targeting irf8, suggesting that increased p53EPS tumor initiation following Irf gene knock-down is a consequence of irf7 and irf8 loss-of-function in the TME." (PMID 39052000, 2024). "Our results from tumor-infiltrating 15.CAR T cells provide evidence that IRF7 and associated factors related to T1IFN signaling indeed play a role in supporting antitumor function in the human TME." (PMID 38645165, 2024). "IRF7 has been implicated in tumor progression and microenvironment-related mechanisms have been proposed, while opposite intrinsic effects on tumor progression were reported in different tumors." (PMID 35256780, 2022). "In melanoma tumor cells, CARM1 ablation induced dsDNA breaks and cGAS-STING activation, together with the increased expression of several ISGs, including Irf7, Ifit1, Oasl1, and Tap1, and the enhancement of tumor cell susceptibility to cytotoxic T cells." (PMID 35493527, 2022). "A previous study reported controversial pro- or anti-oncogenic properties of IRF7 in diverse tumor cells, and the changes in IRF7 expression were associated with DNA damage." (PMID 34830083, 2021). "IHC analysis showed a positive association between IRF3 and IRF7 expression and tumor-infiltrating immune cells, including CD4+ T cell and CD68+ macrophages." (PMID 34488791, 2021). "Analysis of the immune cells at the tumor site and in peripheral blood 30 days post injection, revealed that IRF7 silencing caused an increase in Gr1+CD11b+ cells and a decrease in CD4+, CD8+ T and B lymphocytes in both models." (PMID 30546090, 2019). "It has been shown that in some tumor cell lines delivery of control plasmid DNA caused significant increase in the expression of following ISGs: IRF7, STAT1, MIG, MICA and ITGAL." (PMID 26839680, 2016). "Our results indicate that JX-594 suppressed BAP1-deficient tumor growth through IRF7-dependent IFN-β induction; reactivating this pathway may be a novel therapeutic strategy for RCC." (PMID 40856833, 2025). "IRF5/CSF activation facilitates tumor-associated M2 expression, and IRF7 induces PD-L1 production." (PMID 39384770, 2024). "Additionally, genes associated with tumor cell apoptosis pathways showed overall activation, among which IRF7, DDIT3, and HBEGF were significantly activated." (PMID 38711992, 2024). "Interestingly, among all IRF factors, the mRNA and protein expression levels of IRF3 and IRF7 were significantly upregulated in tumor tissues and associated with poor OS in CRC patients." (PMID 34488791, 2021). "In addition, the innate immune response‐associated genes, including Oas1a, Oas2, Oas3, Ifi202b, Irf7, and Tlr9, were all down‐regulated, indicating a deficiency in anti‐tumor immune response." (PMID 31602788, 2019). "This might be attributed to TGF-β and TNF-α as major soluble factors involved in the functional alteration of tumor associated pDCs, via inhibition of IRF-7 expression and nuclear translocation in pDC after their exposure to tumor-derived supernatants or recombinant TGF-β1 and TNF-α." (PMID 32784928, 2020). "In fact, it has been emphasized that the strengthening of tumour cells immunogenicity, by enhancing the Irf7 axis within own cancerous cells, can significantly enhance the effectiveness of WTCVs and make them a potent option for preventing tumour recurrence." (PMID 41601679, 2026). "In our co-culture system, both the cytotoxic function and mean fluorescence intensity (MFI) of IFN-γ-positive lymphocytes from IRF7-C435A B16F10 tumor-bearing mice were significantly enhanced compared to lymphocytes from IRF7-WT tumor-bearing mice." (PMID 41535256, 2026). "Using single-cell sequencing, we evaluated the regulatory role of IRF7-SNO in the tumor microenvironment." (PMID 41535256, 2026).
tumor (continued). "Here, we found that NOS1 expression induces IRF7 modification by S-nitrosylation at the C435 site in mice (C481 in humans), which functionally promoted tumor growth in mouse models." (PMID 41535256, 2026). "Module 8 was implicated in metabolic regulation and immune responses, such as HNF4A and IRF7, and was upregulated in Il1r2−/− tumor cells." (PMID 40767963, 2025). "Tumor-derived exosomes additionally enhance I-IFN secretion via the circPIK3R3/miR-872-3p/IRF7 axis, boosting the anti-tumor immune response of CD8+ T cells." (PMID 40028322, 2025). "In pancreatic adenocarcinoma, integration of scRNA-seq with ST enabled the identification of an anti-tumour macrophage population marked by IRF7 activity, which limited tumour progression through lipid metabolism-dependent mechanisms." (PMID 40948757, 2025). "We observed significant upregulation of the transcriptional levels of Ifnb1, Ifit1, Ifit2, Ifit3, Irf7, and Mx1 in irradiated 4T1 tumor tissues and irradiated CT26, H22, and GL261 carcinoma cells." (PMID 40470716, 2025). "In TLR2‐/‐ and IRF7‐/‐ mice, the anti‐tumor efficacy and interferon secretion induced by KK2DP7‐mediated training immunity were significantly reduced." (PMID 40145812, 2025). "Given the pivotal role of IRF7 in cancer development and suppression (reviewed in reference 47), this is likely due to the tumor origin of the cells." (PMID 40407345, 2025). "At the same time, the expression of MHC class I-related molecules (H2-D1, H2-K1, H2-T23) and the immune response-related genes Irf7, Ifi27 was increased in Il1r2−/− mouse tumor cells." (PMID 40767963, 2025). "Conversely, Il1r2−/− tumor cells demonstrated higher specificity for regulons controlled by IRF7, HOXB13, and JUND." (PMID 40767963, 2025). "The outcomes demonstrated that the percentage of Ki67‐positive cells in the mouse tumour tissue was reduced in the oe‐IRF7‐Exos + oe‐NC group in comparison to the NC‐Exos + oe‐NC group." (PMID 39118300, 2024). "Our findings indicate that the lipid metabolite content in mouse tumour tissues was decreased in the oe‐IRF7‐Exos + oe‐NC group when juxtaposed with to the NC‐Exos + oe‐NC group, decreasing tumour volume and weight." (PMID 39118300, 2024). "IRF7 activation can induce tumor cells to produce IFNs, activate immune cells, and enhance antitumor immune responses." (PMID 39492838, 2024). "Tracking tumor immunophenotype analysis revealed that the group with high IRF7 expression was highly expressed and correlated with most immune cell recruitment." (PMID 39492838, 2024). "The distribution of these clusters was generally stable across lesion stages, except for tumor-derived pDC_IRF7, DC3_LAMP3, and Mono_CD16 clusters." (PMID 38720887, 2024). "Future research should investigate the potential applications of IRF7/IFNβ in KRAS mutant CRC, as well as the regulation of tumor-associated microbial ecology through the miR3655/SURF6 axis, providing insights into personalized treatment strategies." (PMID 39523457, 2024). "The results indicate that compared to the NC‐Exos + oe‐NC group, the growth rate of tumours in mice from the oe‐IRF7‐Exos + oe‐NC group was inhibited." (PMID 39118300, 2024). "In contrast, the growth rate of tumours in mice from the oe‐IRF7‐Exos + oe‐RPS18 group was even faster than that of the oe‐IRF7‐Exos + oe‐NC group." (PMID 39118300, 2024). "In the tumor region, the metabolism‐related signaling pathway cells were predominantly IRF7 regulon high‐expression locations." (PMID 39492838, 2024). "The tumor suppressive function of IRF7 is mainly related to the production of IFNβ, but IRF7 also promotes the M2 polarization of tumor-associated macrophages and enhances tumor immune evasion and proliferation." (PMID 39329063, 2024). "IRF7 is expressed in the spleen, lymph nodes, and bone marrow, particularly in epithelial cells, monocytes, and macrophages, and promotes tumor growth in some cancers." (PMID 39492838, 2024).
tumor (continued). "Together, the study shows that tumor‐derived exosomes promote I‐IFN secretion via the circPIK3R3/miR‐872‐3p/IRF7 axis in macrophages and enhance the anti‐tumor immune response of CD8+ T cells." (PMID 38286661, 2024). "Conversely, the percentage of Ki67‐positive cells in the mouse tumour tissue encountered a rise in the oe‐IRF7‐Exos + oe‐RPS18 group contrasting with the oe‐IRF7‐Exos + oe‐NC group." (PMID 39118300, 2024). "Similar to AIP, IRF7 has been shown to play complex roles in the tumor microenvironment and can exert oncogenic or tumor suppressor activity, depending on the type of cancer." (PMID 38479600, 2024). "Initially, using RT‐qPCR and Western blot analysis, we observed a notable decrease in the expression of RPS18 and ILF3 in the tumour tissues of mice belonging to the oe‐IRF7‐Exos + oe‐NC group relative to the NC‐Exos + oe‐NC group." (PMID 39118300, 2024). "Nonetheless, RPS18 and ILF3 expression in tumour tissues of mice from the oe‐IRF7‐Exos + oe‐RPS18 group was elevated contrasting with the oe‐IRF7‐Exos + oe‐NC group." (PMID 39118300, 2024). "To examine the expression profile of IRF7 in macrophages infiltrating tumours, we performed flow cytometry analysis to quantify the amounts of IRF7+ M1 and IRF7+ M2 macrophages in adjacent normal tissues and PAAD tissues." (PMID 39118300, 2024). "On the other hand, IRF3 suppresses Wnt/β-catenin to inhibit CRC tumorigenesis and IRF7 activation induces anti-tumor activity in CRC cells." (PMID 39384770, 2024). "We also found that IRF1, IRF3, IRF4, IRF5 and IRF7 were significantly higher in tumor stage III/IV or grade 3/4 compared with tumor stage I/II or grade 1/2, whereas the expression level of IRF6 was lower in tumor stage III/IV or grade 3/4." (PMID 37182129, 2023). "The subpopulation of cells with high expression of BIRC3 was involved in tumor suppressive regulatory role, while IRF7 recruited activated inflammatory cells producing interferons." (PMID 37533434, 2023). "IRF7 also plays an important role in immune escape, cell proliferation and survival of tumor cells by affecting macrophage polarization, NK cell activation, apoptosis, and G-MDSC cell aggregation." (PMID 37251373, 2023). "IRF7 overexpression significantly inhibited tumor growth of Saos-2 cells as demonstrated by reduced tumor weight and tumor volume." (PMID 34975316, 2022). "Using a nude mouse xenograft tumor model, silencing of IRF7 can significantly attenuate tumor growth in vivo." (PMID 34975316, 2022). "Taken together, our study is the first to reveal that IRF7 was downregulated in OS and suppressed the tumor progression and the Warburg effect in OS cells by transcriptional suppression of PKM2." (PMID 34975316, 2022). "Of note, the tumor-suppressive role of IRF7 in tumor growth was largely dependent on the Warburg effect as hijacking glycolysis with galactose largely abrogated cell proliferation induced by IRF7 knockdown." (PMID 34975316, 2022). "Upon genetic manipulation of IRF7 expression, we discovered that IRF7 inhibited aerobic glycolysis and repressed OS tumor growth." (PMID 34975316, 2022). "In a mouse model of bone metastasis, numerous genes controlling interferon regulatory factor 7 (Irf7) were suppressed in response to bone metastasis, which allowed tumor cells to escape immune surveillance and promoted the occurrence of bone metastasis." (PMID 36497209, 2022). "IRF7 belongs to the transcription factor family of interferon regulatory factors (IRFs) and has previously been described to function as a tumor suppressor in multiple cancer types." (PMID 34975316, 2022). "qPCR analysis of the dissociated tumour cells revealed that the delivery of immRNA‐loaded RBCEVs led to the up‐regulation of Ddx58, Mda5, Mavs, Irf3, Irf7, Ifnb, Rsad2, and Isg56 in the tumours." (PMID 35430766, 2022).
tumor (continued). "IRF7 not only affects tumor growth and malignant transformation of various tumor populations, but also regulates the development of myeloid-derived suppressor cells in cancer." (PMID 35692836, 2022). "In contrast, IRF7 knockdown rapidly enhanced the growth of xenograft tumors from KHOS cells as supported by higher tumor weight, larger tumor volume, and more positive staining of Ki67." (PMID 34975316, 2022). "Previously, IRF7 has been demonstrated to play important roles in the tumor initiation and progression of several types of cancers." (PMID 34975316, 2022). "Analysis of scRNA-seq TNBC data further supported the significant association between MUC1 and expression of IRDS genes encoding IRF7, BST2, IFI35 and IFITM1 in individual TNBC tumor cells." (PMID 35681561, 2022). "We also observed positive correlations between IRF3 and IRF7 protein expression levels and markers of tumor-infiltrating immune cell via IHC in 102 cases of CRC." (PMID 34488791, 2021). "Because pDCs are capable of rapidly secreting much higher levels of IFNI than conventional DCs due to constitutive expression of IRF7, they are thought to play a critical role in the initial immune response against tumor cells." (PMID 33801234, 2021). "Altogether, we investigated the IRF family in CRC and revealed that the expression of IRF3 and IRF7 were related to tumor immune infiltration as well as prognosis of patients with CRC." (PMID 34488791, 2021). "We identified Stat3, Irf7, Cox2, and Ifnβ as being up-regulated, while Il1β and Il12α show down-regulation under tumor condition." (PMID 32668709, 2020). "IRF7, a central activator of the interferon type 1 immune response, has oncogenic properties and was shown to both influence tumor growth and malignant transformation in diverse tumor types and to regulate myeloid-derived suppressor cell development in cancer." (PMID 32028264, 2020). "IRF7 silencing in tumor cells or systemic blocking of IFNAR reversed the state of dormancy, while spontaneous escape from dormancy was associated with loss of IFN-β production." (PMID 30546090, 2019). "Taken together, these results demonstrate that elevated expression of IRF7 promotes tumor resistance against chemotherapy and switches the MDSCs-dominated response into a T and B cell-prevalent immune response maintaining dormancy." (PMID 30546090, 2019). "M1 macrophages also express higher levels of Nos2, Cxcl10, and Irf7 and expression of each of these genes increased in the injected tumor in response to combination treatment." (PMID 31921384, 2019). "The protein level of IRF7 was correlated only with that of STAT2 in the tumor tissue but with those of molecules other than STAT2 and IFNAR1 in the normal tissue." (PMID 30305853, 2018). "Adenocarcinoma had lower IRF7 levels in the tumor tissue (p value 0.001) and higher STAT2 expressions in the normal tissue (p value 0.001) than SCC." (PMID 30305853, 2018). "We revealed that the expression of interferon-responsive genes such as Irf7, Rig1 and Mda5 was increased by DNA methylation inhibition in tumor organoids after 5-Aza-CdR treatment or Dnmt1 knockdown." (PMID 28545228, 2017). "These included genes known to be expressed by microglia (CCL8, SPP1, IRF7, IL1RAP), macrophages (IL1RN, SPP1, PDPN, IL1RAP, MDK, TFRC, HRH4), and tumor-associated macrophages (IL6, SPP1)." (PMID 22937035, 2012). "Disruption of IRF7-SNO through the C435 mutation promotes the maturation of DCs and increased the TH1/TH2 ratio, accompanied by enhanced abundance and improved function of CD8+ T cells at tumor sites, as well as augmented cytotoxic activity of NK cells." (PMID 41535256, 2026). "Moreover, the levels of IFN-γ and granzyme B (GZMB) in spleen T lymphocytes, as well as their cytotoxic activity from IRF7-C435A B16F10 tumor-bearing mice, were significantly higher compared to those in the IRF7-WT group." (PMID 41535256, 2026). "Here, we showed that NOS1 induces tumor immune escape through S-nitrosylation of IRF7." (PMID 41535256, 2026).